EZH2 (enhancer of zeste 2 polycomb repressive complex 2 subunit)
Diseases named in the same sentence as EZH2 in open-access papers (continued):
Sharing a sentence is not in itself a finding about the gene and the disease.
breast cancer (continued). "In the current study, the YY1(F219A) and (3A) mutants showed significantly improved binding to EZH2, with simultaneously increased breast cancer cell proliferation and migration, compared to wt YY1." (PMID 35406384, 2022). "EZH2 overexpression is also frequently observed in various malignant tumors, such as breast cancer, resulting in a poor prognostic." (PMID 35326637, 2022). "EZH2 is a transcriptional repressor involved in cell cycle regulation and is related to aggressive breast cancer." (PMID 35813302, 2022). "The expression of HOTAIR is very high in breast cancer metastases and already a small molecular weight inhibitor of the interaction of the EZH2 complex with the 5′ end of HOTAIR has been developed (and see Polycomb section)." (PMID 35406676, 2022). "It is worth mentioning that miRNAs can exert a synergistic impact with anti-tumor agents in regulating EZH2 expression and affecting breast cancer progression." (PMID 35236381, 2022). "This is consistent with previous findings that Tam resistant breast cancer showed a higher expression of EZH2, a H3K27 methyltransferase, compared to the Tam responsive ones." (PMID 35330189, 2022). "In breast cancer, a few studies have demonstrated that EZH2 and HDACs play an indispensable role in breast cancer progression." (PMID 35892859, 2022). "It is also worth noting that the EZH2–CCF–cGAS axis promotes breast cancer progression, and the destruction of this axis by inhibitors weakens cancer cell migration and invasion, thus inhibiting breast cancer metastasis." (PMID 35163710, 2022). "A recent paper discovered that TAMs secrete IL-6 in the TME to stimulate protein arginine methyltransferase 1 (PRMT1)-mediated meR342-EZH2 formation in order to stabilize the enhancer of Zeste Homolog 2 (EZH2) in breast cancer cells." (PMID 35805995, 2022). "On the other hand, EZH2 enhances breast cancer metastasis via epithelial-to-mesenchymal transition (EMT) induction." (PMID 35236381, 2022). "Dysregulation of EZH2, as well as its roles, has been discussed in several solid malignancies including prostate, hepatocellular, colorectal, and breast cancer, as well as in some hematologic malignancies." (PMID 36076977, 2022). "Patients with BRCA1-mutant breast cancer and high EZH2 expression showed an improved therapeutic response and less frequent disease recurrence after treatment with intensified platinum-based chemotherapy, compared to standard chemotherapy." (PMID 35715861, 2022). "For instance, SOX4 overexpression is in favor of breast cancer progression and EZH2 reduces its expression by binding to the promoter, leading to a decrease in invasion and migration of breast cancer cells." (PMID 35236381, 2022). "As well-described epigenetic regulator of cell cycle progression and cell lineage determination, EZH2 overexpression correlates with aggressiveness and poor survival in prostate, colorectal, and breast cancers, as well as melanomas." (PMID 35565249, 2022). "Significantly increased Ezh2 expression in female BRCA1-deficient K14cre; Brca1F/F; Trp53F/F (KB1P) mouse mammary tumors compared to BRCA1-proficient K14cre; Trp53F/F (KP) mammary tumors was further corroborated by RNA sequencing of tumor tissue (p = 0.0156)." (PMID 35715861, 2022). "ANCR-EZH2 binding is required for CDK1 to target EZH2 for ubiquitin–proteasome degradation via Thr-345 and Thr-487 phosphorylation in breast cancer cells." (PMID 35054945, 2022). "Our findings prompted us to test FAK inhibitor for treatment of bone metastases of high EZH2 expressing breast cancers." (PMID 35538070, 2022). "Inhibitors of EZH2 are effective in many cancers, such as lymphoma, melanoma, colorectal cancer, breast cancer, and lung cancer." (PMID 36276954, 2022). "Recently, the Dihua group highlighted EZH2 methytransferase-independent role in breast cancer brain metastasis." (PMID 36446780, 2022).
breast cancer (continued). "Consistently, prior research discovered that EZH2 knockdown resulted in repression of cell proliferation and cell cycle entry in breast cancer, accompanied by a decline in cyclin D1 expression." (PMID 35668081, 2022). "In another study on the role of EZH2 in breast cancer cisplatin resistance, it was shown that Salvianolic acid B promoted vascular normalization in mouse models of breast cancer, which subsequently improved drug delivery and response to cisplatin." (PMID 36230683, 2022). "In breast cancer cells, enhancing expression levels of miRNA-15a and miRNA-16 reduces the EZH2 expression and partially prevents DNA repair and provides DOX sensitivity." (PMID 35236381, 2022). "Very often, EZH2 is associated with the aberrant expression of proteins with a major role in a given cancer, as, for example, BRCA1 in ovarian and breast cancers." (PMID 36230683, 2022). "In breast cancers, where PRC2 activity is elevated in metastatic disease, high levels of enhancer of zeste 2 polycomb repressive complex 2 (EZH2) are associated with repression of TIMP expression via H3K27me3 silencing." (PMID 36066973, 2022). "Combined treatment with the EZH2 inhibitor GSK126 and cisplatin led to increased cytotoxicity and reduced colony formation in BRCA1-deficient mouse mammary tumor cells." (PMID 35715861, 2022). "In case of mutation, LIAS can convert HIF1-α stable in non-hydroxylated form, HIFI-α activation is the basis of the abnormal functional switch of EZH2/PRC2 in breast cancer." (PMID 36699089, 2022). "By examining the Gene Expression Profiling Interactive Analysis (GEPIA) databases, we found that EZH2 was not only upregulated in diverse human cancers but also overexpressed in many different types of breast cancer." (PMID 35085106, 2022). "In breast cancer, impaired activity of ERβ affects the oncogenic activity of NF-kB by inducing outplacement of the EZH2/PRC2 complex and transcriptional repression." (PMID 36556227, 2022). "EZH2 inhibitors were reported to inhibit breast cancer lung metastasis in mouse models, whereas EZH2 inhibitor EPZ-6438 failed to block but promoted bone metastasis in experimental models." (PMID 35538070, 2022). "Analysis of the expression of EZH2 in breast cancer tissue from the TCGA database and in the mentioned authors’ own cohort (RT-qPCR) showed that breast cancer patients with high EZH2 expression had a poor prognosis." (PMID 36230683, 2022). "In line with this, a further study showed that EZH2 was upregulated in cisplatin-resistant breast cancer tissue (tumor tissue from 48 breast cancer patients) and cell lines (MCF-7/CDDP and MDA-MB231/CDDP compared with parental cells)." (PMID 36230683, 2022). "Other researchers found that LncRNA-SCRIT can inhibit the transcriptional activity of EZH2 through direct interaction with EZH2 and regulate the proliferation and invasion of breast cancer cells." (PMID 36699089, 2022). "EZH2 is positively correlated with breast cancer metastasis, invasion, and angiogenesis, and it is a biomarker of invasive breast cancer." (PMID 35163710, 2022). "The positive targeting relationship between SOX5 and EZH2 has been previously identified in breast cancer." (PMID 35468879, 2022). "Studies have demonstrated that EZH2 is significantly up-regulated in various malignancies, including esophageal cancer, breast cancer, gastric cancer, anaplastic thyroid cancer, nasopharyngeal cancer, and endometrial cancer." (PMID 35163710, 2022). "EZH2 enhances breast cancer initiation by directly binding to the NOTCH1 promoter and activates NOTCH1 signaling independent of its catalytic H3K27me3 activity." (PMID 36313363, 2022). "Asymmetrically dimethylated EZH2 by PRMT1 impedes the phosphorylation and ubiquitylation of EZH2 to regulate breast cancer metastasis." (PMID 35921899, 2022). "A previous report revealed that EZH2 contributed to breast cancer chemoresistance by suppressing miR-381 expression via catalyzing H3K27me3 on its promoter region." (PMID 35184652, 2022).
breast cancer (continued). "The role of PRC2 components, especially EZH2, has been proven in a wide range of tumors, including breast cancer, prostate cancer, and lung cancer." (PMID 35565245, 2022). "Only high expression of two genes, including VEGFA and EZH2, indicated unfavorable overall survival of breast cancer patients." (PMID 35812757, 2022). "Significantly higher expression levels of HDAC2 and EZH2 were detected in breast cancer tissues than those in normal tissues, which was consistent with the IHC results for breast cancer and normal breast tissues from the Human Protein Atlas Database." (PMID 35892859, 2022). "Breast cancer is one of the most encountered malignancies among women with miRNAs and EZH2 playing a significant role in proliferation, metastasis, and therapy response." (PMID 35236381, 2022). "Together, data from both cell models and in vivo experiments indicated that EZH2 promoted the vicious cycle of breast cancer bone metastasis, which cannot be blocked by EZH2 methyltransferase inhibitor or the EZH2 H689A methyltransferase dead mutation." (PMID 35538070, 2022). "We found that FAK is a downstream effector of EZH2 in the vicious cycle of breast cancer bone metastasis." (PMID 35538070, 2022). "The expression of enhancer of zeste homolog 2 (EZH2) is correlated with breast cancer metastasis, but its function in bone metastasis hasn’t been well-explored." (PMID 35538070, 2022). "All breast cancer patients with higher EZH2 expression compared to the normal control had significant results." (PMID 35813302, 2022). "Then the effect of EZH2 inhibitors on TAMs polarization and infiltration was assessed in a breast cancer patient-derived xenograft (PDX) model (BC-PDX6305)." (PMID 36038549, 2022). "Herein, we identified that EZH2 performs a crucial role in the regulation of TAMs infiltration and protumoral polarization by interacting with human breast cancer (BC) cells." (PMID 36038549, 2022). "Overexpressing EZH2 under the control of the MMTV promoter (MMTV-EZH2) resulted in the formation of mammary gland hyperplasia and adenomas, the first stage in breast cancer progression." (PMID 33235291, 2021). "Specifically, upregulated EZH2 is capable of promoting proliferation and migration of breast cancer cells 17,18." (PMID 34335938, 2021). "ZLD1039, an EZH2 inhibitor, also exhibited a strong anti-cancer effect by suppressing breast cancer growth and metastasis." (PMID 34360879, 2021). "For example, previous studies have confirmed that PRC2 methyltransferase Enhancer of Zeste Homolog 2 (EZH2) positively regulates breast cancer cell EMT through interaction with SOX4." (PMID 34943943, 2021). "Eventually, disturbed STAT3 methylation by EZH2 in animal model showed decreased breast cancer growth." (PMID 34335938, 2021). "We further find that when comparing breast cancer cases in large cohorts, EZH2 inversely correlates with PTEN expression." (PMID 33750924, 2021). "EZH2 affects the prognosis of breast cancer patients and the choice of EZH2 inhibitory drugs for ovarian cancer." (PMID 34335239, 2021). "A previous report clarified that AKT-mediated EZH2-S21 phosphorylation represses EZH2 methyltransferase activity, leading to a decrease in the amount of H3K27me3 on EZH2 target genes in breast cancer cells." (PMID 34775498, 2021). "It has been vastly reported that EZH2 expression was significantly upregulated in breast cancer patients." (PMID 34335938, 2021). "OGT has been reported to promote EZH2 expression by stabilizing OGT in breast cancer cells while EZH2 has been indicated to facilitate CKD occurrence." (PMID 34462420, 2021). "In breast cancer, EZH2 increases NOTCH1 expression by directly binding to the NOTCH1 promoter and further promotes CSC properties or expands CSCs17." (PMID 33966039, 2021).
breast cancer (continued). "With regard to brain metastasis in breast cancer, a recent study demonstrated that phosholylation of EZH2, which is highly expressed in brain metastatic breast cancer cells, causes c-JUN upregulation and increased G-CSF secretion." (PMID 34405029, 2021). "Here, we reported for the first time that EZH2 exacerbates breast cancer by directly methylating and activating STAT3." (PMID 34335938, 2021). "A previous study found that SOX4 promotes breast cancer metastasis by increasing EZH2 transcription." (PMID 34775498, 2021). "The interaction between EZH2 and STAT3 as well as the STAT3 methylation by EZH2 was also detected in another breast cancer cell line MDA-MB-231 cells as well." (PMID 34335938, 2021). "The expression levels of each hub gene (CENPL, ISG20L2, MRPL3, and LSM4) was correlated with EZH2 in three different breast cancer cell lines (p < 0.01)." (PMID 34341433, 2021). "Although SCIRT is upregulated during the tumorigenesis of breast cancer, it suppresses the cancer cell self-renewal mechanism by counteracting EZH2 and SOX2 to suppress cancer progression." (PMID 34742341, 2021). "RELA has shown an increased methylation level that is significant in the progression of breast cancer, HMOX2 has shown an increased hypomethylation in endometriosis, while EZH2 mediates histone modification H3K27m3 and causes several cancers." (PMID 34788504, 2021). "Based on the PPI networks analysis of robust DEGs, EZH2 was found to be a key gene in the development of breast cancer, and this has been shown in various breast cancer-related studies." (PMID 34341433, 2021). "To investigate the potential role of EZH2-STAT3 axis in breast cancer, we first manifested the role of EZH2 in breast cancer." (PMID 34335938, 2021). "EZH2 overexpression was reported in different cancers, such as prostatic cancer, breast cancer, and uterine cancer, and had worse prognosis in some cancers." (PMID 34257556, 2021). "Altogether, the data support a role for phospho-p38, its upstream MAPK pathway, and EZH2 in the regulation of ERα expression in normal breast and breast cancer." (PMID 34845227, 2021). "EZH2 promotes PTHrP expression via integrin β1 and the knockout of EZH2 inhibit breast cancer-induced bone metastasis." (PMID 34975909, 2021). "We measured PTEN and EZH2 protein expression by IHC in breast cancer cases, and we observed the same inverse correlation." (PMID 33750924, 2021). "In breast cancer, EZH2 activity is reported to be correlated with resistance to HER2-targeted therapy." (PMID 35186711, 2021). "Consistent with OGT’s effects on EZH2, OGT knockdown decreases cellular H3K27 tri-methylation and re-activates a group of EZH2-targeted tumor suppressor genes in breast cancer cells." (PMID 35201498, 2021). "Taken together, our data suggest that PRMT1-mediated meR342-EZH2 inhibits SUZ12 binding with EZH2 by preventing AMPKα1-mediated pT311-EZH2 in breast cancer." (PMID 34775498, 2021). "More relevantly, SMYD2 has been established to coordinate with EZH2 to promote breast cancer tumorigenesis and metastasis." (PMID 34544413, 2021). "Conversely, EZH2 knockout can induce G2/M phase arrest of breast cancer and regulate the expressions of cyclin D1 and β-catenin." (PMID 34335707, 2021). "Twenty-five out of the 27 paths/links connected to metabolic enzyme EZH2 in the breast cancer network possesses at least one gene, whose expression is significantly associated with drug/chemotherapy response." (PMID 34790674, 2021). "In accordance with previous studies, survival analysis showed that EZH2 negatively correlated with the survival probability in breast cancer patients." (PMID 34335938, 2021). "Enhancer of zeste homolog 2 (EZH2) promotes the chemoresistance of breast cancer and other types of cancer by inducing the expansion of TICs." (PMID 33823894, 2021). "EZH2 expression correlates with poor prognosis of colorectal cancer, renal clear cell carcinoma, breast cancer, and bladder cancer." (PMID 33658396, 2021).
breast cancer (continued). "Overexpression of EZH2 indicates a poor prognosis in patients with lymphoma, melanoma, or breast cancer, and EZH2 is considered as a potential therapy target in malignant tumors." (PMID 33743723, 2021). "Above all, these results are consistent with our results mentioned in EZH2-WT inhibiting breast cancer cells proliferation through suppressing P16 and P21 expression in vitro." (PMID 34775498, 2021). "In particular, for breast cancer, BRCA1 associates with EZH2 in a binding region that overlaps with a HOTAIR-binding domain, thus blocking HOTAIR–EZH2 (PRC2) interaction." (PMID 34073224, 2021). "We show that repression of PTEN occurs through the combined action of NOTCH (NOTCH1 or NOTCH2) and EZH2 alterations in a subset of breast cancers." (PMID 33750924, 2021). "Consistently, PcG proteins were also found highly overexpressed in breast cancer, and the high expression of EZH2 in preneoplastic mammary lesions suggests the deregulation of PRC2 activity is an early event in breast cancer development." (PMID 33804165, 2021). "EZH2 was found essential for the proliferation of breast cancer type I susceptibility protein BRCA1-/- cells, while EZH2 overexpression in breast cancer is associated with poor prognosis and correlates with metastatic sporadic and familial breast tumours." (PMID 33804165, 2021). "EZH2 over-expressed in breast cancer patients and regulated STAT3 post-transcriptionally according to TCGA datasets." (PMID 34335938, 2021). "SCIRT plays critical roles in breast cancer, where it counteracts EZH2 and SOX2 to suppresses cancer cell self-renewal mechanism, thereby inhibiting cancer progression." (PMID 34742341, 2021). "High expression of EZH2 is found in breast cancer, prostate cancer, pancreatic cancer, gastric cancer, and other malignant tumors." (PMID 34381492, 2021). "Although numerous efforts have been afforded to unravel the mechanisms of EZH2 involvement in breast cancer, they focus upon the canonical function of EZH2 mostly." (PMID 34335938, 2021). "These phenomena reveal that RES has the potential to hamper EMT stimulated by LPA through suppression of YB-1/EZH2 signaling axis in breast cancer cells, preventing the invasion and metastasis, as well as sensitizing the treatment of 5-FU." (PMID 33937049, 2021). "Overexpression of the FOXP3 protein not only lessened the proliferative effects of EZH2, but also enhanced degradation of the EZH2 protein in breast cancer models." (PMID 33800594, 2021). "For instance, lncRNA NEAT1 upregulated the expression of EZH2 and promoted breast cancer growth by inhibiting miR-101 expression." (PMID 34399848, 2021). "The upregulation of EZH2 expression were shown by TCGA data mining and immunohistochemical staining of breast cancer tissues." (PMID 34335938, 2021). "Breast cancer study revealed that the MAPK pathway mediated the down-regulation of EZH2, contributing to the anti-proliferative effects of curcumin against breast cancer." (PMID 33912467, 2021). "For instance, in breast cancer, EZH2 interacts with β-catenin or members of the NF-κB transcription factor family in estrogen receptor-positive or -negative tumor subtypes, respectively." (PMID 34943970, 2021). "DZNep is one EZH2 inhibitor which reduces EZH2 and induces apoptosis in colon and breast cancer cells, although its affinity for other HMTs has limited its application." (PMID 34064704, 2021). "EZH2 is highly expressed in a series of cancers, including ovarian cancer, breast cancer, prostate cancer and kidney cancer, and plays an important role in cancer tumorigenesis and progression." (PMID 33718109, 2020). "EZH2 has been identified as an oncogene in breast cancer that functions by epigenetically inhibiting the expression of various tumor suppressor genes." (PMID 32754259, 2020). "Professor Wong's team first provided convincing evidence on OGT-mediated EZH2 O-GlcNAcylation at S75 in breast cancer." (PMID 33308321, 2020).